ADCY1 (adenylate cyclase 1)
Diseases named in the same sentence as ADCY1 in open-access papers (continued):
Sharing a sentence is not in itself a finding about the gene and the disease.
infection (2 papers, 2022 to 2024). The state of being infected such as from the introduction of a foreign agent such as serum, vaccine, antigenic substance or organism. "Concentrations of each inhibitor used were those previously published in the literature although it was noted that some caused increased cytotoxicity during testing on RAW 264.7 cells, and this was exacerbated by infection in the case of the Adcy1 inhibitor ST034307." (PMID 38916198, 2024). "So, while ST034307 inhibition of Adcy1 function significantly decreased intracellular LF82rpsmGFP at 24 hpi, it was seen to induce increases in cytotoxicity when used at the effective 10 μM concentration, with this increase in cytotoxicity becoming significant upon infection." (PMID 38916198, 2024).
neurological disorders (2 papers, 2017 to 2020). "Adcy1 is predominantly expressed in the central nervous system (CNS), making it an attractive drug target for the treatment of neurological disorders." (PMID 33297570, 2020).
brain diseases (1 paper, 2019). "As a member of adenylate cyclase (ADCY), ADCY1 was first found to be expressed abundantly in brain and subsequent studies was mainly focused on its role in brain diseases." (PMID 31839819, 2019).
heart disease (1 paper, 2016). "Clinical and epidemiologic research suggest that reduction of ADCY1 expression has well-documented benefits, including benefits for heart disease and pain." (PMID 27598154, 2016).
ADCY1 also shares sentences with these, for which no sentence is quoted: Anxiety (2 papers); prostate carcinoma (2); type 2 diabetes mellitus (2); adenocarcinoma (1); alcohol addiction (1); amyotrophic lateral sclerosis (1); autoimmune thyroid disease (1); bone tumors (1); brain tumors (1); breast tumor (1); cholera (1); ciliopathy (1); Cirrhosis (1); colon (1); colorectal cancer (1); cyst (1); endometriosis (1); female infertility (1); gastric cancer (1); head and neck cancer (1); heart failure (1); Herpes simplex infection (1); idiopathic pulmonary fibrosis (1); Kidney Cyst (1); leukemia (1); lung squamous cell carcinoma (1); malaria (1); McCune-Albright syndrome (1); mood disorder (1); nephronophthisis (1).
A further 5 diseases each share a sentence with ADCY1 in 1 paper.